LTB (lymphotoxin beta)
Description:
Cytokine that binds to LTBR/TNFRSF3. May play a specific role in immune response regulation. Provides the membrane anchor for the attachment of the heterotrimeric complex to the cell surface. Isoform 2 is probably non-functional.
Synonyms: TNFC; TNFSF3; p33; TNLG1C
Tractability: Antibody: its Gene Ontology location is reachable by antibodies, with high confidence; UniProt predicts a signal peptide or a membrane-spanning region. Other modalities: a drug acting on it is in phase 2 or 3 trials.
Target class: Secreted protein
Safety:
Unwanted effects reported when the protein is acted on. In parentheses: how it was acted on, where the effect was seen, and who reports it.
hypersensitivity (source: ClinPGx)
Gene: Protein-coding gene on chromosome 6 (31,580,525 to 31,582,522, reverse strand). Ensembl gene ENSG00000227507.
Subcellular location: Membrane
Subcellular location (Human Protein Atlas): Centrosome
Pathways (Reactome):
Immune System: TNF receptor superfamily (TNFSF) members mediating non-canonical NF-kB pathway; TNFR2 non-canonical NF-kB pathway
Gene Ontology:
Molecular function: cytokine activity; signaling receptor binding; tumor necrosis factor receptor binding
Biological process: activation of NF-kappaB-inducing kinase activity; cell surface receptor signaling pathway; cell-cell signaling; dendritic cell homeostasis; positive regulation of canonical NF-kappaB signal transduction; positive regulation of extrinsic apoptotic signaling pathway; positive regulation of interleukin-12 production; regulation of necroptotic process; regulation of type I interferon production; signal transduction; cell communication; immune response; signaling
Cellular component: plasma membrane; tumor necrosis factor receptor superfamily complex; membrane
Genetic constraint (gnomAD): Loss-of-function variants: 20 observed, 15.85 expected, observed/expected ratio (o/e) 1.26, 90% interval 0.88 to 1.78. The upper end of that interval is the gene's LOEUF score, 1.78, which puts it in group 6 of 6, group 1 being the genes least tolerant of losing a copy. Missense variants: 288 observed, 316.61 expected, observed/expected ratio (o/e) 0.91, 90% interval 0.82 to 1. Synonymous variants: 163 observed, 158.29 expected, observed/expected ratio (o/e) 1.03, 90% interval 0.91 to 1.17.
Homologues: Orthologues: chimpanzee LTB (99% identical), macaque LTB (97% identical), pig LTB (84% identical), rabbit LTB (84% identical), dog LTB (80% identical), mouse Ltb (75% identical), rat Ltb (75% identical), guinea pig LTB (71% identical), tropical clawed frog ltb (25% identical). Paralogues in human: TNFSF14 (23% identical), LTA (23% identical), TNF (21% identical), TNFSF15 (21% identical), FASLG (20% identical), TNFSF10 (18% identical), TNFSF11 (18% identical), CD40LG (17% identical).
Diseases named in the same sentence as LTB in open-access papers:
LTB is named in the same sentence as 98 diseases in open-access papers, as found by Europe PMC text mining. Sharing a sentence is not in itself a finding about the gene and the disease. The quoted sentences say what the papers report.
breast carcinoma (6 papers, 2014 to 2024). "In keeping, loss of tumour HEVs and LTB expression seem to be critical steps during breast cancer progression." (PMID 35201443, 2021). "In human breast cancer, DCs produce high levels of LTβ and the density of mature DC-LAMP+ DCs strongly correlates with the frequency of HEVs." (PMID 34122434, 2021). "Finally, LTB was expressed only in 3 cases of breast cancer; it was expressed only in neoplastic cells (positivity percentage ranging from 15 to 60%), with non-tumour ducts and TILs always being negative." (PMID 35201443, 2021). "MacroH2A1.2 reduces bone metastasis by attenuating the activity of lymphotoxin beta (LTβ) in prostate cancer and inhibiting secretion of lysyl oxidase (LOX) in breast cancer, thus exerting an anti-osteoclastogenic effect." (PMID 39199381, 2024). "In human tumors, DCs are a major source of LTβ and their density correlates with HEV formation and favorable clinical outcome in breast cancer." (PMID 34122434, 2021).
COVID-19 (6 papers, 2020 to 2022). A disease caused by infection with severe acute respiratory syndrome coronavirus 2. "Cytokine-related genes that were found to be dysregulated in both CAD patients and COVID-19 patients include chemokines (CCL3 and CCL4), chemokine receptor CXCR1, and a TNFSF gene, LTB." (PMID 34071557, 2021). "In the present study, LTB-RBD (a chimeric protein comprising a mucosal adjuvant carrier (LTB) and a segment from the RBD of SARS-CoV-2) was produced and purified as an antigen vaccine candidate for the formulation of mucosal vaccines against COVID-19." (PMID 36298624, 2022). "Notably, in severe/critical COVID-19 patients in the recovery stage, the proportion of CD14 monocytes (based on the expression of the marker genes CST3, LYZ, CD14) in PBMCs were elevated, but CD4 T cells (IL7R, LTB) were decreased, consistent with a previous report." (PMID 35046942, 2021).
lymphoma (6 papers, 2012 to 2023). A malignant (clonal) proliferation of B- lymphocytes or T- lymphocytes which involves the lymph nodes, bone marrow and/or extranodal sites. "The expression of the LTβR in BECs and its ligands Ltα, Ltβ, and Tnfsf14 (LIGHT) in DCs remained unchanged in lymphoma." (PMID 34706240, 2021).
cholera (4 papers, 2019 to 2026). "As CTB is immunologically cross-reactive to LTB, the B subunit from LT, an immune response generated to CTB would potentially contribute to protection against diarrhea caused by LT-producing ETEC with a CTB-containing whole cell cholera vaccine." (PMID 32176708, 2020). "The CT B-pentamer is a component of the major cholera vaccine, and the binding of CTB or LTB to cells has been shown to enhance immunogenicity." (PMID 30736336, 2019).
hepatocellular carcinoma (4 papers, 2013 to 2023). A malignant tumor that arises from hepatocytes. "The upregulation of LTB and its downstream targets, CXCL10 and NF-κB, was associated with tumorigenesis in HCV-related hepatocellular carcinoma (HCC)." (PMID 33397394, 2021). "We found that ITM2A, LTB, TNFRSF4, and TNFRSF18 were significantly overexpressed in hepatocellular carcinoma cell lines (Hep3B and Huh7) relative to normal liver cell lines (HL-7702)." (PMID 37006257, 2023). "To investigate the mechanism of LTβ induction by HCV proteins, we turned to a full-length HCV replicon propagated in Huh7 human hepatoma cells: the Nneo/C-5B model." (PMID 23555249, 2013).
psoriasis (4 papers, 2019 to 2024). An autoimmune condition characterized by red, well-delineated plaques with silvery scales that are usually on the extensor surfaces and scalp. "Other validated psoriasis susceptibility genes were ERAP2 (5q15), IL18R1 (2q12.1), LTB (12p13.31), IL1RL1 (2q12.1), CARD14 (17q25.3), and SLC9A4 (2q12.1)." (PMID 36425068, 2022).
rheumatoid arthritis (4 papers, 2017 to 2024). A chronic, systemic autoimmune disorder characterized by inflammation in the synovial membranes and articular surfaces. "With respect to cardiac development, LTB is identified as a risk factor altered for cardiovascular diseases and thus the TNF antagonist potentially acts as a likely candidate to reduce the CVD risk in rheumatoid arthritis patients." (PMID 29026152, 2017).
Sepsis (4 papers, 2018 to 2026). Sepsis is defined as life-threatening organ dysfunction caused by a dysregulated host response to infection. "Collectively, FFAR2, MAPK14, LTB, SAMD9L shown dysregulation in all three studies, indicating their roles at both cellular and system-level responses to sepsis." (PMID 30086151, 2018). "Although studies have shown a direct correlation between LT-α and sepsis, direct evidence for a correlation between LTB and sepsis is lacking in studies." (PMID 36389695, 2022).
viral infections (4 papers, 2021 to 2025). "In the lymph node, LTB–LTBR signaling between B cells and macrophages maintains macrophage responsivity to viral infections, and microglial LTBR has roles in de- and remyelination." (PMID 36333772, 2022). "Furthermore, expression levels of pro−inflammatory cytokines such as IL−32, LTB, and MIF were markedly elevated in the severe group, with IL−32 persistently upregulated across all disease stages, reinforcing its known pro−inflammatory role in viral infections and lung pathology." (PMID 41200182, 2025).
Autoimmunity (3 papers, 2012 to 2025). The occurrence of an immune reaction against the organism's own cells or tissues. "LTB is involved in chronic inflammation and autoimmunity and LTB antibodies have been tested for inhibiting LTB mediated inflammation." (PMID 23140489, 2012). "The LTB-LTBR axis is known to be both pathogenic and drug-responsive across multiple autoimmune-affected organs (skin, joints, eyes), reinforcing its relevance to autoimmunity and highlighting its potential as a therapeutic target in immune-mediated CKD40,41." (PMID 41282674, 2025). "Moreover, LTB deficiency has been shown to prevent autoimmunity in non-obese diabetic mice, allergic encephalomyelitis, and experimental murine colitis models." (PMID 34440439, 2021).
colitis (3 papers, 2018 to 2021). Inflammation of the colon. "Thus, to determine whether LTαβ contributes to LTβR protective effects in in DSS-induced colitis, LTβ deficient mice were treated with DSS." (PMID 30524422, 2018). "The fundamental conundrum is that mice deficient for LTβR expression have a different phenotype in DSS colitis from mice deficient for both of its known ligands, LIGHT and LTβ." (PMID 30524422, 2018). "To directly test the hypothesis that LTβ-LTβR signals drive severe colitis, we crossed two strains to generate double knock out (DKO) mice deficient for LTαβ and LTβR and determined if these mice exhibited augmented DSS-induced colitis progression." (PMID 30524422, 2018). "LTβR-dependent effects of LTβ in moderating severe colitis due to expression by T cells are not ruled out by our work, however, and overall the data indicate how the analysis of cell-type-specific effects of gene deficiency are essential in this complex system of ligands and receptors." (PMID 33568785, 2021). "Given that LIGHT protects from exacerbated DSS-induced colitis and that LTαβ does not contribute to enhanced colitis progression, we hypothesized that mice deficient for both LIGHT and LTβ would develop augmented colitis." (PMID 30524422, 2018).
melanoma (3 papers, 2006 to 2025). A malignant, usually aggressive tumor composed of atypical, neoplastic melanocytes. "Thus LTB conjugated to OVA peptides induced CD8+ T cells that protected against OVA-loaded melanoma." (PMID 27375923, 2013).
myeloma (3 papers, 2016 to 2025).
prostate carcinoma (3 papers, 2021 to 2024). A carcinoma that arises from epithelial cells of the prostate gland. "They include calcium channel-encoding genes, the cell fate determinant and cold-shock protein LIN28B in bladder cancer and lymphotoxin beta (LTβ) in prostate cancer." (PMID 34203934, 2021). "Furthermore, macroH2A1.2 can also inhibit prostate cancer induced osteoclastogenesis via direct interactions with HP1α and H1.2, turn out inactivating a major stimulator of osteoclastogenesis, Lymphotoxin Beta (LTβ) gene in prostate cancer cells." (PMID 38542118, 2024).
autoimmune disease (2 papers, 2013 to 2020). A disorder resulting from loss of function or tissue destruction of an organ or multiple organs, arising from humoral or cellular immune responses of the individual to their own tissue constituents. "The lymphotoxin-alpha (LTα) and lymphotoxin-beta (LTβ) pathways have been associated with the presence of ectopic lymphoid structures at the sites of chronic inflammation in several autoimmune diseases." (PMID 24286296, 2013). "Increased levels of LTα and LTβ molecules, and their activation, have been associated with the presence of ectopic lymphoid structures at sites of chronic inflammation in several autoimmune diseases." (PMID 24286296, 2013).
breast tumors (2 papers, 2017 to 2020). "Martinet and colleagues demonstrated that DC-LAMP+ DCs were the major producers of LTβ in human breast tumors and that LTβ is overexpressed specifically in tumors displaying a high density of HEVs." (PMID 29312327, 2017).
bronchiectasis (2 papers, 2020 to 2021). Segmental, irreversible dilation of the bronchial tree resulting in the accumulation of secretions which leads to obstruction. "A recent study identified different inflammation profiles when comparing gingival tissues of bronchiectasis patients having chronic periodontitis, with 7 genes significantly altered in bronchiectasis patients (LTA, LTB, TNFSF4, TNFSF11, TNFSF13, TNFSF13B, and TNFRSF11B)." (PMID 34765263, 2021).
colorectal cancer (2 papers, 2022 to 2024). A primary or metastatic malignant neoplasm that affects the colon or rectum. "In T3/T4 colorectal cancer, the number of NKp44+ ILC3s and the expression of LTA, LTB, and TNF, but not ILC3-related molecules (e.g., RORC, IL22, and IL17A), in these cells were decreased." (PMID 39327633, 2024).
diabetes (2 papers, 2021 to 2025). "Interestingly, one NKT like cell cluster high expressing LTB was found, which is consistent with the report from Humphreys lab, and LTB level was higher in lymphocyte of diabetes than that of control." (PMID 33754492, 2021).
head and neck squamous cell carcinoma (2 papers, 2021 to 2022). A squamous cell carcinoma that arises from any of the following anatomic sites: lip and oral cavity, nasal cavity, paranasal sinuses, pharynx, larynx, and salivary glands. "Additionally, LTB also interacted with methylated epithelial growth factor receptor (EGFR) in head and neck squamous cell carcinoma (HNSCC) to induce cetuximab resistance, leading to unfavourable outcomes." (PMID 33397394, 2021). "Although there is no direct study on whether LTB promotes or suppresses the TSCC mechanism, our findings suggest that LTB is a key molecule in mediating snail-induced cetuximab resistance in head and neck squamous cell carcinoma." (PMID 36567723, 2022).
lupus (2 papers, 2025). "In our lupus model, increasing proinflammatory cytokines such as Cxcl13, Ccl19, Ltβ, and Baff mRNA levels trigger the TLOs formation." (PMID 40651955, 2025). "Indeed, LTB-LTBR signaling is up-regulated in human kidneys with inflammatory glomerulonephritis, and LTBR blockade in mouse lupus models improves kidney function." (PMID 41282674, 2025).
oral cancer (2 papers, 2020 to 2025). "A three-gene expression signature including IL-7, LTB, and CXCL13 was associated with LN neogenesis in human oral cancer, where higher grades of TLS were associated with improved disease-free survival (DFS) and overall survival (OS)." (PMID 40475770, 2025).
parasitemia (2 papers, 2008 to 2020). "This could include comparison of parasitemia kinetics, disease susceptibility and parasite-specific B cell responses in intact and splenectomised WT mice and LTβ−/− mice." (PMID 32582198, 2020). "As the infection progressed the LTβ−/− mice were unable to successfully control the parasitemia when compared to WT mice." (PMID 32582198, 2020). "In contrast, five of eight of the LTβ−/− mice relapsed between 21 and 30 dpi, displaying subsequent parasitemia waves." (PMID 32582198, 2020). "Conversely, the organized splenic microarchitecture in WT mice and WT → LTβ−/− mice coincided with their increased ability to control subsequent parasitemia waves." (PMID 32582198, 2020). "Although LTβ−/− mice were able to control the first parasitemia wave as effectively as wild-type mice, they were unable to control subsequent parasitemia waves." (PMID 32582198, 2020). "This implies that the reduced ability of the LTβ−/− mice to effectively control the parasitemia during the later stages of the infection was at least in part a consequence of their reduced ability to produce parasite-specific class-switched IgG antibodies." (PMID 32582198, 2020). "Furthermore, the onset and duration of the first detectable parasitemia wave in the bloodstream of each mouse group was similar: WT mice, 6–8 d post-infection (dpi); LTβ−/− mice, 5–7 dpi." (PMID 32582198, 2020). "Furthermore, the mean parasite burdens at the peak of the first parasitemia wave were also similar in each mouse group: WT mice, 8 × 106/ml parasites/ml; LTβ−/− mice, 1 × 107 parasites/ml; P = 0.460, Student's t-test, n = 8/group." (PMID 32582198, 2020). "In contrast, none of the WT → LTβ−/− mice, and only one of eight of the ID injected un-irradiated WT mice, had any detectable relapses in their parasitemias during the remainder of the experiment." (PMID 32582198, 2020). "Since LTβ−/− mice lacked the draining lymph nodes it is possible that these effects were avoided, enabling a higher burden of parasites to initially enter the blood-stream, leading to the slightly earlier development of the first parasitemia peak." (PMID 32582198, 2020). "Subsequent experiments suggested that the inability of LTβ−/− mice to control the subsequent parasitemia waves coincided with the lack of organized B cell follicles in their spleens, and their impaired ability to mount parasite-specific Ig isotype class-switched antibody responses." (PMID 32582198, 2020). "Although the LTβ−/− mice lacked most peripheral lymph nodes, had disorganized microarchitecture within their spleens and lacked the ability to mount trypanosome-specific class-switched IgG responses, the magnitude and duration of the initial parasitemia wave was similar when compared to WT mice." (PMID 32582198, 2020).
sarcoidosis (2 papers, 2024 to 2025). Sarcoidosis is a multisystemic disorder of unknown cause characterized by the formation of immune granulomas in involved organs. "Th1 and Th17.1 cells in sarcoidosis-affected skin induced NF-κB–associated inflammatory genes, including LTB, TNF, CCR6, and IL6." (PMID 39225100, 2024). "At the same time, LTB may also play a role in the sustained inflammation observed in sarcoidosis granulomas, making it a potential therapeutic target." (PMID 39824903, 2025).
sarcoma (2 papers, 2021 to 2025). A usually aggressive malignant neoplasm of the soft tissue or bone. "In the NanoString data, we detected a 5‐fold increase of LTB and a 3.6‐fold increase of L‐selectin in the aggregates compared with the adjacent sarcoma tissue, suggesting that the stimulus for HEV formation is within the tumour." (PMID 39462771, 2025). "PAX5 and LTB proteins were shown to be significantly downregulated in the tumour cells of primary sarcomas with metastasis based on IHC." (PMID 33397394, 2021). "However, PAX5 and LTB proteins were shown to be significantly downregulated in the tumour cells of primary sarcomas with metastasis." (PMID 33397394, 2021). "The results of the Mann–Whitney U test suggested that PAX5 (P < 0.001) and LTB (P < 0.001) were all highly expressed in well-differentiated primary sarcomas and primary sarcomas without metastasis." (PMID 33397394, 2021).
tuberculosis (2 papers, 2015 to 2024). A chronic, recurrent infection caused by the bacterium Mycobacterium tuberculosis. "Their detrimental role during the progression to tuberculosis is well documented, with the interferon signature, as indicated by the expression of ISGs, being highly detected in patients with tuberculosis, in contrast to those with LTB." (PMID 39062562, 2024).
abscesses (1 paper, 2019). "During the process, the activated neutrophils and microphages start degranulation when contacting foreign components like LtB and NapA, and form abscesses and epithelial erosions." (PMID 31461854, 2019).
allergic asthma (1 paper, 2014). A asthma with a basis in a pathological type I hypersensitivity reaction. "A recent study discovered that LTB, the B subunit of LT, protected mice from OVA-induced allergic asthma by inducing regulatory T cells." (PMID 24637787, 2014).